CD4 (CD4 molecule)
Diseases named in the same sentence as CD4 in open-access papers (continued):
Sharing a sentence is not in itself a finding about the gene and the disease.
infection (continued). "Our results indicate that while both CD4 and CD8 T cells are responsible for acute disease in ML29 infection, ML29 induces significant hearing loss in a mechanism independent of either CD4 or CD8 T cells." (PMID 36289695, 2022). "(A–I) GP66-specific splenic CD4 T cells were isolated and sort-purified from two individual LCMV Clone 13 (Cl13)-infected mice on day 10 post-infection, and the 10× Genomics pipeline was used to generate a combined single cell RNA-sequencing (scRNA-seq) + T cell receptor (TCR) seq library." (PMID 36255051, 2022). "HIV-1 Env trimers that favor State 3 can mediate infection of target cells with low or no CD4 expression (44, 53, 62, –, 70)." (PMID 35323042, 2022). "Notre patiente était indemne de l'infection à VIH, diabète, drépanocytose, hépatites virales B et C, insuffisance rénale, cancer, thérapie immunosuppressive, et avait un taux de CD4 à 750 cellules/mm3, mais était atteinte de TBp évolutive et de dénutrition." (PMID 36815177, 2022). "In agreement, a recent report shows that infected CD4+ T cells promote infection of alveolar macrophages by non-M-tropic primary HIV-1 isolates." (PMID 35622876, 2022). "Indeed, Csf2-/-/μMT mice had a reduced number of CD4+ T cells in tracheobronchial lymph node as well as in lungs and BAL 4 days post-infection." (PMID 35493510, 2022). "Consistently, flow cytometry of intracellular cytokine staining showed that M2e and N2-specific CD4+ T and CD8+ T cells, which secrete IFN-γ, were substantially increased in the lung of m-cNA-M2e VLP group compared to the naïve infection group." (PMID 36006890, 2022). "Re-infection to the same animals, however, was quickly eradicated and accompanied by a strong intrahepatic CD8+T-mediated cytolytic activity together with an expansion of peripheral CD4+ and CD8+ memory T-cell response." (PMID 35267563, 2022). "Overall, these data indicate that infection with R5/X4 HIV-GKO in the presence of IL-15 or IL-2 does not change the distribution of CD4+ T lymphocytes." (PMID 35499323, 2022). "Furthermore, both CD8+ and CD4+ Ag-specific T cells in the BAL up-regulated markers of tissue residence, CD69 and CD103, between days 7 and 10 post-infection." (PMID 35271298, 2022). "Furthermore, CD4+ and CD8+ SARS-CoV-2 spike-specific T cell responses triggered by prior infection with the original strain or BNT 162b2 vaccination, remain largely intact against the Omicron strain." (PMID 35833134, 2022). "The half-life of memory CD4+ T cells to smallpox vaccination was estimated to be about 8–15 years, whereas SARS-CoV T cells were detected 17 years after the initial infection." (PMID 35018336, 2022). "Moreover, studies on T cells reported that the impact of mutations present in VoCs is limited and that the majority of CD4+ and CD8+ T-cell responses are preserved in both vaccinated and natural infection conditions being directed against conserved T epitopes." (PMID 35757699, 2022). "infection did not develop until T-lymphocyte (CD4) counts were maintained at >180 cells/mL, and 87% of HIV-positive patients with lower lymphocyte counts developed a full-blown chronic infection." (PMID 35628973, 2022). "More importantly, the tolerogenic phenotype of DCs is partly reverted in IDO1-/- mice, as indicated by enhanced activation, proliferation, and differentiation of both CD4+ and CD8+ - T cells upon infection with Echinococcus multilocularis, in comparison with WT mice." (PMID 36439161, 2022). "The CD4+ cells also showed a mixed pattern, with higher CD226 (activation) and Tim-3 (inhibitory) expression and lower GITR (activation), CD223 and B7H5 (inhibitory) expression after secondary infection." (PMID 35743356, 2022). "Based on adoptive transfer of mutant virus-specific T cells, this work has also shown that E protein residues 151 and 304 are the key determinants of protection against lethal infection and neutralizing antibody production mediated by TMUV-specific CD4+ T cells." (PMID 36016955, 2022).
infection (continued). "Specifically, a subpopulation of CD4+ T cells could support the production of anti-SARS-CoV-2 antibodies, and cytotoxic CD8+ T cells are also protective against the infection." (PMID 36447270, 2022). "Although in proliferation assays, CD8+ T cells were propagated more than CD4+ T cells in response to re-stimulation, the number of CD4+ T cells but not CD8+ T cells expressing IFN-γ increased after infection with H. pylori SS1 in the spleen of immunized mice." (PMID 36466847, 2022). "Interestingly, the memory phenotype of the activated SARS-CoV-2-specific CD4+ T cells in adults showed a shift from mainly TEM to a more TCM phenotype at 10 months after infection; TCM subset increased from 3.7% to 17.6% of the antigen-specific CD4+ T cells." (PMID 35197982, 2022). "Therefore, the absence of an adequate expansion of CD8+ T-cells, leading to higher CD4/CD8 ratios, has a deleterious impact on the prognosis of the infection in terms of in-hospital mortality but also in ARDS incidence." (PMID 35814752, 2022). "HIV studies utilizing humanized myeloid-only-mice (MoM) demonstrated the ability of macrophages to maintain infection without CD4 cells." (PMID 35062339, 2022). "The expression of CD11b, CD4, CD14, and CD68 for M0; IL-6, HLA/DRA, and CXCL10 for M21, and IL-10, CD163, fibronectin-1 or FN1, and CCL17 was evaluated by qPCR at 2 and 24 h after infection." (PMID 35889103, 2022). "Considering this population, we designed a chimeric multiepitope vaccine that should stimulate the production of specific antibodies, CD4 + and CD8 + T cells to control and prevent viral spread without risk of infection." (PMID 34997041, 2022). "Furthermore, lectins have the potential to inhibit the virion infection of HIV-1 toward the host CD4+ T-lymphocyte cells by interacting with HIV envelope glycoproteins gp120 and gp41 and binding the CD4+, CXCR4, or CCR5 receptors." (PMID 35892945, 2022). "In addition, immunological memory of CD4+ and CD8+ T cells is induced upon infection, which is primarily directed to conserved viral antigen peptides and formulate cross-reactivity with different subtypes in influenza A virus reinfection." (PMID 35317717, 2022). "Furthermore, the proportion and activation of CD4+ T cells and CD8+ T cells decreased significantly with the increase of MDSCs at 6–7 weeks after infection." (PMID 36279265, 2022). "The DCs then migrate to lung-draining mediastinal lymph nodes (MLNs) and to spleen via afferent lymphatic vessels where they prime CD4+ and CD8+ T cells 2 – 3 days post infection (dpi) by establishing stable contacts resulting in activation of antigen-specific T cells." (PMID 36275685, 2022). "And the significant increases of IFN-γ-producing CD4+ T cells frequency were also found in the LN and spleens of KO rats following infection with S. japonicum, but not in the blood." (PMID 35584107, 2022). "Previous studies have shown both CD4+ and CD8+ T cells cooperate synergistically in hMPV eradication during primary infection, with the CD4+ T cells contributing more to clinical disease and lung pathology and CD8+ T cells contributing significantly to viral clearance." (PMID 35958551, 2022). "Because CD4+ T cells were dispensable, we considered whether other cells might be sources of IFN-γ during the initial infection stages." (PMID 35133985, 2022). "In the MLN, CD4+ T cells were the dominant population of CD45+ IL-10+ cells in both naïve and infected animals, although the proportion of B cells and ILCs within the IL-10+ pool increased slightly upon infection." (PMID 35428872, 2022). "Secondly, due to the lack of CD4 and new infection detection data of these cases, we cannot judge that all individuals are recently infected." (PMID 35799101, 2022). "Therefore, increasing IL-17, CD4, and CD8 T cells can improve powerful immune response initiation and recruitment of immune cells such as neutrophils to the infection site." (PMID 35656187, 2022).
infection (continued). "In addition, another study has shown that the percentages of CD4+ and CD8+ T cells concomitantly increase from day 7 after infection and persist for 7 days as the symptoms disappear." (PMID 35475648, 2022). "We then sought to determine whether adjunctive ZOL/IL-2 administrations, while expanding anti-TB Vγ2Vδ2 T effector cells and facilitating immune responses of CD4+ Th1 or CD8+ T effectors, led to immune resistance to MDR-Mtb V791 infection." (PMID 35765887, 2022). "Noteworthy, the infection itself failed to induce detectable M2e-specific CD4 T cells in unimmunized control mice." (PMID 35260804, 2022). "Of the CD3+ cells, a higher percentage of CD4+ T cells, but not CD8+ T cells, from IL-10-deficient mice produced TGFβ1 at both 5 and 7 days after infection compared to WT mice." (PMID 36016413, 2022). "BCGΔBCG1419c elicited T cell memory responses represented by the robust induction of antigen-specific polyfunctional effector memory CD4+/CD8+ CD44+CD62L- T cell responses before and after infection, and it especially induced CD8+ T cells more than BCG did prior to challenge." (PMID 36138053, 2022). "They found that lung tissue γ/δ T cells are stimulated C. neoformans Δsgl1, even in absence of CD4+ T cells, and they are responsible for inducing protection against a secondary infection in mice." (PMID 36354897, 2022). "Later, trafficking of CD4+ T cells increased in all ARV-infected groups, and infiltration of both CD4+ and CD8+ T lymphocyte population continued to markedly increase at day 9 post-infection and were significantly higher (p < 0.0001) compared to the saline control group." (PMID 35369435, 2022). "Thus, we integrated the history of HIV-1 diagnosis, baseline CD4+ T-cell count and HIV-1 RNA level and our RRITS results to determine the infection status of HIV-1 patients." (PMID 36483196, 2022). "Our findings indicate that, despite B-cell depletion and a lack of B-cell—T-cell interaction, a robust virus-specific CD4+ T-cell response can be primed that helps to control the viral replication, but which is not sufficient to fully abrogate the infection." (PMID 35746736, 2022). "The CD4 depletion model does not account for individual variability in CD4 cell counts nor variability in CD4 cell count depletion owing to other factors including alcohol use, pregnancy, other infections, or other chronic conditions." (PMID 36962254, 2022). "Since we observed lower IL‐10 levels in the spleen and lung of Sema3E-Fc treated mice and Treg is one of the primary sources of this cytokine, we next examined CD4+ CD25+ Foxp3+ T cells in the lungs of WT and Sema3E KO mice treated with Sema3E-Fc following Cm infection." (PMID 35983029, 2022). "Although Chlamydia is often referred to as a “Th1 pathogen” due to prominent CD4 T cell IFN-γ production and the high susceptibility of IFN-γ-deficient mice, our data show that mice lacking T-bet can control FRT infection with essentially normal kinetics." (PMID 35196366, 2022). "We observed that CD4+GATA3+ T cells increased significantly in the MLN after both primary and challenge infections compared to uninfected mice, but their numbers were significantly lower after primary infection compared to challenge infection." (PMID 35757733, 2022). "We then measured the levels of infection from nonpermissive Raji producer cells to the Raji/CD4/R5 cells with or without peptides through inLuc transduction." (PMID 35073736, 2022). "Although they do not prevent infection, CD4+ T cells are indispensable for the generation of protective antibody responses and supporting the maturation of CD8+ T cells." (PMID 35102311, 2022). "Both CD4+ and CD8+ T cells are required for optimal control of chronic MHV68 infection." (PMID 35968944, 2022). "The significant increase in IL-8 gene expression in both CD4+ and CD8+ T cells together with increased ex vivo IL-8 protein expression (data not shown) show that T cells are also a significant source of IL-8 during MABS infection." (PMID 36439147, 2022).
infection (continued). "Through flow cytometric analysis that employed cell surface marker staining, our data revealed that there were an increased number of CD4+ T cells and CD8+ T cells in ascites at an early stage of infection (day 4) by OH2(n = 12) compared with PBS‐ (n = 6) or fluorouracil (n = 6)‐treated tumors." (PMID 35510373, 2022). "In this protracted infection model, which did not involve experimental CD4 T cell ablation, we also observed reduction of viral loads after B cell therapy." (PMID 35958615, 2022). "Inguinal lymph node CD4+ T cells but not CD8+ T cells or B cells also upregulated PD-1 following infection." (PMID 36265003, 2022). "We decided to isolate both T-cell subpopulations CD4+ and CD8+ as well as CD20+ B-cells and CD14+ monocytes, since interaction of these cells was hypothesized earlier to be relevant for infection (also see Discussion)." (PMID 35359920, 2022). "The preoperative CD4+/CD8+ lymphocyte ratio in patients with infection significantly decreased in comparison with the one without infection (1.05 ± 0.44 vs. 1.72 ± 0.69)." (PMID 36169250, 2022). "Despite robust replication in lymphoid tissues, there is only transient infection of gut CD4+ T cells, no detectable infection of macrophages, and little to no immune activation." (PMID 35714165, 2022). "IFN-γ production was dampened in worm-infected mice also in response to polyclonal restimulation but the numbers of Tbet+ CD4+ T cells (TH1) were not altered by the infection." (PMID 34931000, 2022). "T cell lipid peroxidation induces ferroptosis and reduces immunity to infection, and Gpx4 is critical for the homeostatic survival of CD8 T cells and the expansion of CD4+ and CD8+ T cells in response to infection by preventing membrane lipid peroxidation and ferroptosis upon TCR triggering." (PMID 35990689, 2022). "Indeed, the numbers of CD4+ and CD8+ T cells in the spleen of resistant mice strains increase rapidly during infection and are maintained at a high level before migrating into the brain before the onset of experimental CM." (PMID 36014972, 2022). "In the early infection stage, the B.m+B16 group showed no significant change in the proportion of CD4+ T cells, CD8+ T cells, NK cells, and macrophages in the spleen compared to the B16 group." (PMID 35814662, 2022). "At weeks 4, 6, 8 and 10, the percentage of CD4+ effector memory T cells (Tem, CD44+CD62L-) was higher than that of the control group, and it was significantly increased at week 4 and represented 93.04% of CD4+ T cells after infection." (PMID 36046744, 2022). "We have therefore studied the dynamics of CD4 and CD8 T cells targeting the vaccine-encoded Spike and the non-encoded Nucleocapsid antigens during breakthrough infections (BTI, n=24) and in unvaccinated control infections (non-BTI, n=30)." (PMID 36582222, 2022). "Infection with rPS-YE significantly increased the levels of IL-2, IL-17, TNF-β, and CD8 in brain and thymus, CD4 in brain, and IFN- γ in thymus, and significantly reduced the levels of IFN-γ in brain and CD4 in thymus, as compared to those observed for the parental backbone virus rPS." (PMID 36016955, 2022). "Inhibition of infection with FTY720 involves blocks at multiple levels of the HIV-1 life cycle and suggests the requirement of S1P binding to S1P receptors for the progression of infection in CD4 T cells." (PMID 35412343, 2022). "Pulmonary infection with C. neoformans elicited strong CD8+ T-cell responses to control the infection independent of CD4+ T cells." (PMID 36177012, 2022). "Additionally, the hyperfunction of CD4+ and CD8+ T cells is correlated with the pathogenesis of severe infection." (PMID 36250073, 2022). "Because infection of CD4+ T cells is the key difference between HIV and other infectious pathogens, and HIV propagates better in the activated CD4+ T cells, a narrower spectrum of HIV Gag epitope recognition by a protective HLA class I allele appears to make sense." (PMID 35746714, 2022).
infection (continued). "A higher population of CD4+ T and memory B cell responses in the spleen were observed in VLPs-immunized mice than non-immunized control upon challenge infection." (PMID 35214662, 2022). "Compared to cell-free infection, infected T-cell/MΦ contacts showed enhanced interactions of R5 M- and non-M-tropic Envs with CD4 and CCR5, resulting in a reduced dependence on receptor expression levels on MΦ for viral entry." (PMID 35622876, 2022). "Importantly, the numbers of Ag-experienced CD4 and CD8 T cells were significantly increased in SPexp 25 d after initial infection in the blood." (PMID 35878936, 2022). "CD4+ and CD8+ T cells are important for regulating the host’s immune function against infection." (PMID 35584107, 2022). "The preferential infection of CD45RA− memory T cell populations rather than the CD45RA+ naive population is in agreement with HIV-1 being predominantly detected in memory CD4+ T cells in vivo." (PMID 35417711, 2022). "Our group has identified abortive infection and pyroptotic programmed cell death as a major driver of the cell death occurring in lymphoid tissue-derived but not blood-derived CD4 T cells." (PMID 35784348, 2022). "Flow cytometric analysis demonstrated similar absolute concentrations of total leukocytes, total lymphocytes, B cells (CD19+), NK cells (CD3−, CD56+), T cell (CD3+), CD4+ T cells, and CD8+ T cells between previously infected, recently infected, and infection-naïve HCWs." (PMID 36560542, 2022). "HSV-specific CD4 T cells occur mostly in the dermis after recovery from infection and are not as restricted to the site of primary infection." (PMID 35432373, 2022). "IL-10 and IFNγ CD4+ cells are important for a chronic, nonresolving infection status, and together with the elevated TNFα and IL-6 expression, these data fit well with the enhanced and prolonged inflammation in the colons of AOM/DSS-treated CerS4 LCK/Cre mice." (PMID 35163788, 2022). "In spite of that, another group showed that the same epitope activated CD4+ T cells in more donors who got breakthrough infections after vaccination than in vaccinated donors who had no breakthrough infection." (PMID 36447270, 2022). "In untreated HIV infection, regular activation of intrinsically long-lived provirus-containing (“latently infected”) CD4+ T cells, rather than continuous chains of virus production and infection, is responsible for sustained infection." (PMID 36761169, 2022). "As these are ubiquitous bacteria in the environment, the presence of memory CD4 and CD8 cells may indicate previous exposure in the form of subclinical infection or intermittent colonisation in the damaged lungs." (PMID 35548464, 2022). "CD4 has a critical role in immunity and has been suggested to have some signatures of positive selection in species without historical infection by SIV (e.g. humans)." (PMID 36007015, 2022). "Neutrophils, B lymphocytes, CD4+ and CD8+ T lymphocytes were quantified in the lungs of female and male mice of each experimental group by flow cytometry to address the cellular immune response after hMPV infection." (PMID 36159799, 2022). "In contrast to HIV-1, infection with LP-BM5 retrovirus targets highly immunosuppressive myeloid suppressor cells, which severely dampen both T and B cell functions, whereas HIV-1 directly infects CD4 Th cells." (PMID 35203323, 2022). "In contrast, after immunization and infection with V. anguillarum, the percentage of CD4+ cells did not change significantly within the first 12 h (p > 0.05), was lightly decreased at hour 24 (p < 0.05), and then increased to the peak at 48 h (p < 0.05)." (PMID 36363767, 2022). "All of the experiments above utilized a model of chronic infection induced by experimental CD4 T cell depletion at the time of challenge, because without experimental CD4 T cell ablation it is not possible to induce a stringent lifelong multi-organ infection." (PMID 35958615, 2022).